STAT3 (signal transducer and activator of transcription 3)
Diseases named in the same sentence as STAT3 in open-access papers (continued):
Sharing a sentence is not in itself a finding about the gene and the disease.
glioma (continued). "STAT3 is considered a potential therapeutic target for glioma, but there is no effective targeted STAT3 clinical treatment method for glioma." (PMID 34425834, 2021). "As the literature has not revealed relevant findings, glioma-related studies should focus more attention on lncRNAs and circRNAs involved in the STAT3 signalling pathway of immune cells." (PMID 34425834, 2021). "The DA-induced suppression of NF-κΒ and STAT3 activity is not specific only to endothelial cells, as it has also been demonstrated in other cells, including chondrocytes, glioma cells, and hepatocytes." (PMID 35008877, 2021). "STAT3, a downstream molecule of JAK2, is a member of the family of the signal transducer and activator of transcription (STAT), which is constitutively activated in most cancers, including glioma." (PMID 33959183, 2021). "In glioma, JAK2/STAT3 signaling may regulate the expression of E‐cadherin, N‐cadherin, vimentin, and β‐catenin via related transcription factors to inhibit the EMT process." (PMID 33788424, 2021). "The enhanced invasion may be mediated by an IL-6-induced increase in STAT3 signaling and upregulation of MMP2 in glioma cells." (PMID 34503065, 2021). "As Phosphorylation of STAT3 would induce its nuclear translocation to modulate target gene expression, we also evaluated the effect of CYB561D2 on the subcellular distribution of STAT3-GFP in glioma cell lines." (PMID 34372858, 2021). "In glioma, IFN-β regulates miR-21 through STAT3, which is an interesting finding." (PMID 34425834, 2021). "Moreover, lncRNA NEAT1 promotes glioma pathogenesis though many of other pathways including NEAT1/miR-449b-5p/c-Met axis, NEAT1/MiR-92b, TLR9/NEAT1/STAT3, NEAT1/microRNA let-7e, miR-152-3p/CCT6A, and miR-139-5p/CDK6." (PMID 33393590, 2021). "Radiation induces the secretion of exosomes by glioma cells containing proteins involved in numerous crucial signaling pathways including JAK/STAT, as well as proteins such as ribophorin II, which signal through STAT3 to promote anti-apoptosis via Mcl1." (PMID 33498872, 2021). "Moreover, through attenuating the miR-384/PIWIL4/STAT3 axis, CRNDE promotes malignant progression in glioma cells." (PMID 34454479, 2021). "Interestingly, VEGF also activated angiogenesis through STAT3 phosphorylation, and co-inhibition of the receptors for both leptin and VEGF suppressed angiogenesis in HUVECs induced by conditioned medium from glioma cells more than either antagonist alone." (PMID 33316976, 2020). "Therefore, ADV infection likely triggers TLR9/MYD88 signaling, which upregulated NEAT1 and activated STAT3, and activated STAT3 further upregulates NEAT1 to form a positive-feedback loop, and promotes GSCs formation from primary glioma cells." (PMID 32843056, 2020). "The western blot analysis indicated that knockdown of PDCD4 in glioma cells enhanced p-STAT3 levels, but not p-ERK or p-FAK1." (PMID 33304903, 2020). "However, downregulation of miR-30a can inhibit the JAK/STAT3 pathway by targeting SOCS3 and reducing the tumor-forming ability of glioma stem cells." (PMID 32273831, 2020). "Previous studies have demonstrated that IL‐6 recruits gp130 by binding to its receptor, the membrane‐bound IL‐6 receptor (mIL‐6R), to activate STAT3.36, 37, 38 Moreover, CD9 stabilizes gp130 to activate STAT3 in glioma stem cells by preventing its ubiquitin‐dependent lysosomal degradation." (PMID 31837208, 2020). "In addition, microarray analysis revealed that the PDGFB-driven glioma had a significant increase in other anti-inflammatory (M2) mediators, including IL1R2, IRF7, and STAT3." (PMID 33020472, 2020). "In fact, there is currently no comprehensive analysis of STAT3 expression in gliomas, particularly with respect to immunosuppression." (PMID 32483429, 2020).
glioma (continued). "Given the inhibitory effects by SRT2183 on glioma cell growth, we examined whether SRT2183 affects the acetylation of STAT3 and NF-κB, two well-known substrates of Sirt1 in glioma cells." (PMID 31319814, 2019). "Admittedly, there are other known cytokines that activate STAT3, e.g. IL-4 and -13, and therefore the dependence of our results on IL-6 effect alone is not confirmed as of yet, as it requires validation in other glioma cell lines outside of the ones we tested." (PMID 31361777, 2019). "Significant expression of the leptin receptor has been shown in CD133+ cells and knockdown of leptin receptor effectively lowered the invasiveness of stem-like cells in gliomas and confirmed that JAK/STAT3 signaling is the molecular mechanism involved in the invasion of U87 glioma cells." (PMID 30803210, 2019). "Specifically, they demonstrated that C/EBPβ and STAT3 were (i) responsible for MGES expression, (ii) able to reprogram neuronal stem cells towards a MES phenotype, and (iii) responsible for the aggressiveness traits of glioma cells." (PMID 31167470, 2019). "Furthermore, STAT3-mediated activation of miR-182-5p had been shown to upregulate the proliferative and invasive capacities by directly targeting PCDH8 in glioma cells." (PMID 30927925, 2019). "We showed that CDK5 regulates glioma tumorigenicity by promoting TRIM59 nuclear translocation via PIN1/importin α5 axis, leading to STAT3 signaling activation, and demonstrate that CDK5 mediates EGFR-stimulated STAT3 signaling through activation of the TRIM59/mH2A1 axis in GBM." (PMID 31488827, 2019). "Moreover, the tumor suppressive effect of AP-2α was exerted through inhibiting the transcriptional activity of the Nanog gene and the IL6/STAT3 signaling pathway to attenuate the stemness and TMZ resistance of glioma cells." (PMID 31534499, 2019). "Moreover, miR-26a alleviated the inhibitory effect of AP-2α and the miR-26a inhibitor on glioma cells by upregulating the expression of Nanog/Sox2 and the IL6/Jak2/STAT3 signaling pathway." (PMID 31534499, 2019). "Of interest, we observed a profound decrease in the phosphorylation levels of STAT3 in SRT2183-treated glioma cells while the acetylation of STAT3 at Lys-685 was not significantly affected." (PMID 31319814, 2019). "Up to now, however, the associations between STAT3 and FOXP1 expression in human glioma have not been examined." (PMID 30134017, 2018). "Although PIAS3 is closely associated with STAT3 and Smad6 interacts to PIAS3, we did not observe direct interaction between Smad6 and STAT3 in glioma cells." (PMID 29950561, 2018). "In contrast, the expression of Ki67 and STAT3 target genes (CCND1 and SOX2) were significantly reduced in the MH2-treated xenografts, indicating a therapeutic effect of TAT-MH2-NLS protein for glioma." (PMID 29950561, 2018). "Moreover, EGFR, phosphorylated STAT3, CD133 and Nestin expression was reduced in xenografted glioma tissues in response to honokiol treatment, which was consistent with in vitro results we observed." (PMID 30587839, 2018). "We found that YM155 reversed EMT in glioma cells and prevented radiation-induced in vitro and in vivo invasion, and that YM155 might elicit these activities through inhibition of STAT3." (PMID 29571296, 2018). "In addition to that, among the human glioma cells including SHG‐44, U87, GOS‐3 and TJ905, U87 and SHG‐44 were with the highest and the second highest mRNA and protein levels of STAT3, respectively, which were selected as the main experimental subject." (PMID 30134017, 2018). "In the last decade Stat3 has gained attention as therapeutic target in cancer but there is not yet any approved Stat3-based glioma therapy." (PMID 28157712, 2017).
glioma (continued). "Interestingly, compared with vector control-transduced cells, glioma cells with ATM knockout showed significantly less CD133 expression and reduced levels of activated STAT3." (PMID 28337983, 2017). "Targeted IL-13Rα2 knockdown showed only modestly reduced or no detectable change in STAT3 in wtEGFR-expressing cell line and primary glioma cultures derived from GBM patient tumors, respectively." (PMID 29203859, 2017). "In conclusion, we could infer that Coptis Chinensis down-regulated the phosphorylated STAT3 level by reducing the expression of HDAC3 protein, which then affected the function of glioma cells and their biological characteristics." (PMID 29212474, 2017). "Gene associated with retinoid-interferon-induced mortality-19 (GRIM-19) has been recognized as a tumor suppressor protein, which regulates cell growth, apoptosis, and migration by signal transducer and activator of transcription 3 (STAT3) signaling pathway and non-STAT3 pathway in glioma cells." (PMID 29074558, 2017). "Our study demonstrates for the first time that SR-A1 could inhibit TAM differentiation toward an M2-like phenotype by suppressing STAT3 and STAT6 signaling in murine gliomas." (PMID 27367025, 2016). "Strikingly, overexpression of Oct4 in C6 cells was able to increase the expression of Nestin and Stat3 phosphorylation while decreasing the expression of GFAP, which suggests that Oct4 might inhibit the differentiation of glioma cells." (PMID 26381429, 2016). "Moreover, treatment of glioma cells with IL-6 upregulated RTVP-1 expression and activation of the RTVP-1 promoter in glioma cells via activation of STAT3." (PMID 26267319, 2015). "We then analyzed whether the expression of STAT3 and ANGPTL4 was correlated with glioma grade in the TCGA database." (PMID 25955030, 2015). "Here, we show that EGFRvIII induces the expression and secretion of pigment epithelium-derived factor (PEDF) via activation of signal transducer and activator of transcription 3 (STAT3), thereby promoting self-renewal and tumor progression of glioma stem cells (GSCs)." (PMID 25992628, 2015). "Indeed, SR141716 impacts U251 and primary glioma cells growth and MICA/B expression through the specific inhibition of activated STAT3, a transcription factor harboring both oncogenic and immunosuppressive functions." (PMID 26008966, 2015). "In addition, GCN5 knockdown reduced expression of p-STAT3, p-AKT, PCNA and MMP9 and increased the expression of p21 in glioma cells." (PMID 26378521, 2015). "The expression of C/EBPβ and STAT3 correlates with the mesenchymal phenotype of GBM and predicts poor clinical outcome and these two TF have been demonstrated to regulate the mesenchymal transformation of glioma cells." (PMID 26267319, 2015). "Constitutively activated STAT3 and VEGF receptors can be coexpressed in glioma." (PMID 24518612, 2014). "We thus attempted to determine if VPA altered the levels of STAT3 in glioma cells in the presence or absence of oHSV infection." (PMID 23936533, 2013). "Furthermore, STAT3 target molecules such as IL-10 and IL-6 have been shown to activate STAT3, leading Li and Graeber to propose a feed-forward mechanism which may account for the constitutive activation of STAT3 in both glioma cells and glioma-infiltrating TAMs." (PMID 23737783, 2013). "Taken in conjunction, VPA’s mechanism of action through STAT3 activation and ISG reduction would explain the enhanced replication of oHSV, although it is likely that VPA may increase oHSV replication in gliomas though other pathways as well." (PMID 23936533, 2013). "The mechanism of activity of the combination of cediranib and AZD1480 however is not exclusively confined to the inhibition of STAT3 expressing macrophages in the glioma since the combinational approach also inhibited nestin." (PMID 23013619, 2012).
glioma (continued). "Since the STAT3 signaling pathway may play a major role as a master regulator of glioma pathogenesis, HCMV gene products that promote STAT3 transcriptional activation could influence glioma biology." (PMID 22030012, 2011). "Because JSI-124 has been shown to pharmacologically inhibit STAT3 phosphorylation, we hypothesized that the combination of dasatinib and JSI-124 might cooperate to block glioma cell proliferation and induce apoptosis." (PMID 20808823, 2010). "In human glioma cells, it has been shown thattroglitazone activates protein-tyrosine phosphatase-1B (PTP-1B), whichsubsequently reduces phosphotyrosine 705 STAT3 (pY705-STAT3) via a PPARγ-independent pathway.Reduction of pY705-STAT3 in glioma cells caused downregulation of c-FLIP andBcl-2." (PMID 18615184, 2008). "In glioma, M2-like TAMs could maintain the CSC status via integrin αvβ5-Src-Stat3 signaling." (PMID 39897030, 2025). "Notably, overexpression of miR-30 is observed in glioma stem cells; downregulation of miR-30 reduces SOCS3 suppression, activating the JAK/STAT3 signaling pathway, thus confirming the regulatory role of the miR-30/SOCS3/JAK/STAT3 axis." (PMID 40642530, 2025). "Moreover, this study did not include preclinical or clinical assessments of STAT3 inhibition in gliomas driven by F3-T3." (PMID 40265014, 2025). "Moreover, the formulation better countered the immunosuppressive glioma microenvironment by reducing M2 macrophage polarization via the suppression of IRF4 transcription and diminished phosphorylation of STAT6, STAT3, and AKT, thereby undermining a key mechanism of glioma immune evasion." (PMID 40284496, 2025). "Interestingly, glioma tissue displayed an increase in pSTAT3 levels upon ITE+PD1 treatment, suggesting that IL-11 and IL-6 are likely not the primary regulators of STAT3 in this context and highlighting STAT3 as a potential target for combination therapy." (PMID 40283908, 2025). "Exosomes loaded with STAT3 inhibitors that enter the brain by crossing the BBB, after nasal administration, are selectively taken up by microglia and inhibit the expression of inflammatory cytokines, such as IL-1β and IL-6, ultimately retarding glioma cell growth." (PMID 38890722, 2024). "In glioblastomas after bevacizumab therapy, hypoxia can persistently induce the expression of phosphorylated signal transducer and activator of transcription 3 (p-STAT3) in glioma cells, which preserves the mesenchymal transformation of normal neuroglial cells and the stemness of glioma cells." (PMID 38787372, 2024). "Additionally, the JAK/STAT3 signaling pathway, NF-κB signaling pathway, and immune microenvironment disruptions appear to be key pathways involved in the regulation of LINC00324 in glioma." (PMID 38530810, 2024). "In gliomas, T cell tolerance can result from peripheral deletion of T cells through Fas-L-mediated apoptosis or through the immunosuppressive effect of Tregs, which in turn is induced by upregulated expression of IDO1 and the signal transducer and activator of transcription 3 (STAT3)." (PMID 38275375, 2023). "In our study, we are the first to report that in glioma, the FOSL1 induction occurred at the transcriptional level in a manner dependent on STAT3, during which phosphorylated post-translational modification was required for STAT3 activation to directly bind to the FOSL1 promoter (ChIP)." (PMID 37642779, 2023). "Furthermore, IL-6 treated glioma cells could upregulate the expression of RTVP-1 and enhance the RTVP-1 promoter activity by activating STAT3." (PMID 36923251, 2023). "Furthermore, inhibition of PIAS3 by RNA interference in the U87-MG human glioma cell line promoted cell proliferation despite less or no change in STAT3 phosphorylation." (PMID 36923251, 2023).
glioma (continued). "In addition, the catalytic subunit brahma related gene 1 (BRG1) of the SWI/SNF complex can maintain the stemness of glioma‐initiating cells by inhibiting the STAT3/TXNIP pathway, resulting in the resistance of glioma‐initiating cells to the chemotherapeutic drugs temozolomide (TMZ) and carmustine." (PMID 37576862, 2023). "With the assistance of bioinformatic prediction tools, as well as ChIP and luciferase reporter assays, STAT3 was identified as a transcription factor responsible for LINC00662 up-regulation in OS cells by binding to the LINC00662 promoter region, consistent with a previous report in glioma." (PMID 36334221, 2023). "In other cancer types, including glioma and HCC, LBX2-AS1 affects cell proliferation and apoptosis through the miR-491-5p-leukemia inhibitory factor (LIF)-signal transducer and activator of transcription 3 (STAT3) and miR-384-insulin receptor substrate 1 (IRS1) pathways, respectively." (PMID 36131071, 2023). "Besides, our results further revealed that the upregulation of ARSD, which promoted glioma cell proliferation, migration and invasion, could be effectively inhibited by the JAK2/STAT3 pathway inhibitor AG490." (PMID 37766864, 2023). "However, no other associations with pre-diagnostic glioma were found in any of the other allergy related transcription factors that were investigated (forkhead box p3 (FOXP3), signal transducer and activator of transcription 3 (STAT3) and STAT6)." (PMID 37265788, 2023). "Moreover, the enrichment of an epithelial-mesenchymal transition signature as well as STAT3 signaling markers in poor-surviving groups further characterize these results, suggesting a role of M0 macrophage abundance in the MES-like cell state in glioma." (PMID 35144680, 2022). "Phosphorylation of STAT3 and JAK2 was significantly enhanced in glioma cells, and inhibition of IL-6/JAK2/STAT3 signaling pathway could significantly inhibit the proliferation of glioma cells and promote cell apoptosis." (PMID 36591515, 2022). "In addition, STAT3’s interaction with hypoxia-inducible factor 1 (HIF-1) and vascular endothelial growth factor (VEGF) under local hypoxic conditions can increase VEGF expression and glioma angiogenesis." (PMID 36497459, 2022). "By exploring the B7-H4 level in glioma tissues with different grades, Yao and their colleagues found that the cross-talk between glioma-initiating cells and macrophages mediated by B7-H4 through the IL6/JAK/STAT3 pathway could result in poor prognosis." (PMID 33539322, 2021). "A lack of negative STAT3 regulation also contributes to its constitutive activation in gliomas." (PMID 33498872, 2021). "To clarify the role of JAK2/STAT3 signaling in glioma EMT and determine whether NC modulates JAK2/STAT3 signaling as a mechanism for inhibiting EMT in glioma cells, we used WP1066 to inhibit JAK2/STAT3 activity in U87 and LN18 glioma cells during exposure to TGF‐β1 for the induction of EMT." (PMID 33788424, 2021). "Finally, we established intracranial glioma model in nude mice and mice were randomly assigned to Control group (n = 13), CYB561D2 over-expression group (n = 13) and CYB561D2 over-expression plus dominant negative STAT3 over-expression group (n = 13)." (PMID 34372858, 2021). "Our preliminary data showed that a STAT3 inhibitor could inhibited UBE2D3 overexpression-induced STAT3 phosphorylation in glioma cells (data not shown)." (PMID 34195079, 2021). "As research continues, an increasing interest in the function of CRNDE in glioma reveals that CRNDE could modulate glioma cell growth and invasion with EGFR activation and through mTOR signaling, and promote malignant progression by attenuating miR-384/PIWIL4/STAT3 axis in GBM." (PMID 34454479, 2021). "Another study demonstrated that administration of a STAT3-targeting miR-124 in combination with a T cell co-stimulatory aptamer was able to increase CD4+ and CD8+ T cells and decrease macrophage trafficking into the TME in a genetically engineered murine glioma model." (PMID 33498872, 2021).